DMD (dystrophin)
Diseases named in the same sentence as DMD in open-access papers (continued):
Sharing a sentence is not in itself a finding about the gene and the disease.
muscular dystrophy (380 papers, 2006 to 2026). Muscular dystrophy (MD) refers to a group of more than 30 genetic diseases characterized by progressive weakness and degeneration of the skeletal muscles that control movement. "DMD is the most common form of childhood muscular dystrophy and is caused by mutations in the DMD gene that encodes for dystrophin protein." (PMID 40189894, 2026). "Sarcoglycan delta (SGCD) encodes a crucial component of the dystrophin-glycoprotein complex, and variants in this gene have been implicated in both muscular dystrophies and cardiomyopathies." (PMID 41840602, 2026). "Our study of chronic and acute muscle regeneration in the mdx mouse provides a comprehensive overview of muscular dystrophy progression and contributes valuable insight into the altered dynamics and function of dystrophin‐deficient MuSCs." (PMID 39723578, 2025). "Muscular dystrophy is a neuromuscular disorder, part of which is caused by the deficiency of dystrophin protein and is mostly related to genetics." (PMID 40034097, 2025). "Current research on Muscular Dystrophies (MD) suggests that its occurrence is closely related to several mechanisms, including gene mutations, dystrophin deficiency, and alterations in the Akt/mTOR/p70S6K signaling pathway." (PMID 41195013, 2025). "Unfortunately, Case 4 has limited diagnostic information with no available CK activity; however, the clinical signs are presumed to be caused by muscular dystrophy as this dog was also positive for the DMD variant." (PMID 41300820, 2025). "Dystrophin‐associated glycoprotein complex‐mediated cell linkage to the ECM is often disrupted in muscular dystrophy, with deficient interaction between laminin and α‐dystroglycan comprising an essential characteristic of secondary dystroglycanopathies." (PMID 39923120, 2025). "Similar sex differences in this assay have been reported in female mdx mice, a mouse model of dystrophin-deficient muscular dystrophy, and attributed to estrogen availability." (PMID 40309777, 2025). "This study describes a novel deletion in DMD gene exon 5 that is likely causative of dystrophin-deficient muscular dystrophy in a family of Shiba Inu dogs with X-linked inheritance." (PMID 41300820, 2025). "Muscular dystrophies are a group of genetic disorders characterized by progressive muscle weakness and degeneration, caused by defective dystrophin." (PMID 41166051, 2025). "The variable severity of clinical phenotypes in canine models and human dystrophin-deficient muscular dystrophy is well known, which can be a complication in the interpretation of clinical trials." (PMID 41300820, 2025). "Total intravenous anesthesia is recommended in people with dystrophin-deficient muscular dystrophy and should also be considered for dogs undergoing general anesthesia if a myopathy is suspected." (PMID 41300820, 2025). "Muscular dystrophies are additionally associated with neurodevelopmental disorders, thought second to dystrophin's expression in the brain." (PMID 39915227, 2025). "Although the progression of muscular dystrophy in mdx mice is less severe compared to humans, both dystrophin‐deficient mouse and human muscles display characteristic lesions, elevated inflammation and similar mechanisms of dysregulation." (PMID 39723578, 2025). "One category of muscular dystrophies is known as dystrophinopathies, which results from mutations in the Dystrophin (DMD) gene, the largest gene in the human genome, which encodes the protein dystrophin." (PMID 40282342, 2025). "A subgroup of muscular dystrophies linked to genetic defects hitting the members of the so-called dystrophin–glycoprotein complex (DGC) has been identified." (PMID 40422224, 2025). "Enhancing SSPN expression can be used to stabilize the membrane and reduce disease severity in both dystrophin and γ-SG deficiency, demonstrating therapeutic potential for treating muscular dystrophies." (PMID 40549548, 2025).
muscular dystrophy (continued). "A specific subgroup of muscular dystrophies is associated with genetic defects in components of the dystrophin–glycoprotein complex (DGC), which plays a crucial role in linking the cytosol to the skeletal muscle basement membrane." (PMID 40422224, 2025). "Dystrophin-deficient muscular dystrophy (dystrophinopathy) is a major subset of muscular dystrophies, resulting from variants in the DMD gene, which encodes the dystrophin protein and is located on the short arm of the X chromosome." (PMID 41300820, 2025). "The first murine muscular dystrophy model mdx was discovered over 40 years ago as a naturally occurring dystrophin mutation in a research colony of C57Bl6 mice; however, there are now over 60 mutant and transgenic mouse models used for DMD research alone." (PMID 39425123, 2024). "Using WGS, a DMD p.F1125* frameshift/stop-gain variant was identified, confirming the dog had X-linked dystrophin-deficient muscular dystrophy." (PMID 38473107, 2024). "Mutations in various components of the dystrophin protein complex lead to different types of autosomally inherited muscular dystrophies, highlighting the significance of this complex in healthy muscle function." (PMID 39292690, 2024). "Nevertheless, both approaches have been used to correct mutations or deficiencies in genes causing muscular dystrophies, as well as for delivery of the DMD or mini-DMD coding sequence, many studies on which have been reviewed elsewhere." (PMID 38607035, 2024). "The CK activity, however, was markedly elevated in the dystrophic dog, and elevation of CK activity can help to differentiate a dystrophin-deficient muscular dystrophy from other early-onset inherited myopathies." (PMID 38473107, 2024). "Thrombospondin-4 is an extracellular protein involved in extracellular matrix assembly, and if mutated gives rise to muscular dystrophy, similar to other structural proteins such as dystrophin and collagen." (PMID 39627572, 2024). "Of note, CA1 has already been described as serum biomarker in dystrophin deficient muscular dystrophy." (PMID 38652110, 2024). "Mutations in the DMD gene, leading to the absence or dysfunction of the dystrophin protein causing muscular dystrophies in humans, were associated with muscle fat replacement." (PMID 37337145, 2023). "Since the complete absence of dystrophin expression causes severe muscular dystrophy, DMD-null mice were thought to be an improved model for functional studies of dystrophin and its isoforms." (PMID 36928364, 2023). "Duchenne (DMD) and Becker (BMD) muscular dystrophies are X-linked recessive disorders caused by mutations in the dystrophin gene." (PMID 37697356, 2023). "Our findings in the Bangladeshi study cohort have identified novel pathogenic variants of the DMD gene and other phenotype-muscular dystrophy associated genes, thereby expanding the human mutational database and the spectrum of DMD-related pathogenesis." (PMID 38057384, 2023). "Compared to archived control muscle, immunofluorescent staining was absent for the rod- and carboxy-terminus of dystrophin in all three cases, with upregulation of utrophin consistent with a diagnosis of a dystrophin-deficient muscular dystrophy." (PMID 37628610, 2023). "The combination of MLPA and NGS is a valuable approach for detecting mutations in the Dystrophin gene in Peruvian patients suspected of muscular dystrophies." (PMID 37759719, 2023). "Comparative proteomics previously revealed muscular dystrophy caused by mutations in dystrophin leads to an upregulation of ECM proteins such as collagen and fibronectin." (PMID 38187633, 2023). "Severe types of muscular dystrophy in patients with in-frame deletions in the DMD gene were related to mutation sites, dystrophin expression levels, or resultant dystrophin lengths." (PMID 37298068, 2023).
muscular dystrophy (continued). "DMD, the most severe and common muscular dystrophy that early mimics age‐related muscular atrophy, is a severe progressive muscle disease caused by mutations in the gene encoding dystrophin." (PMID 36935171, 2023). "The results indicate that out of 14 participants, 13 carried pathogenic or clinically relevant mutations in DMD and/or its associated muscular dystrophy genes." (PMID 38057384, 2023). "Although LGMD2C is considered a recessive form of muscular dystrophy as severe as DMD, the inheritance pattern is a clinical hallmark to distinguish them." (PMID 36992678, 2023). "This new specific ROIMB has been designed to quantify fluorescence staining in sarcolemmal or subsarcolemmal regions, such as the dystrophin-glycoproteins complex, where mutations in the genes encoding for its components can cause several muscular dystrophies." (PMID 37612778, 2023). "Dogs with muscular dystrophy show muscle dystrophy and atrophy with sometimes macroglossia, and various deleterious DMD variants have been described in several canine breeds (OMIA #001081-9615)." (PMID 36834603, 2023). "When the gene encoding muscle dystrophin is mutated, the truncated dystrophin prevents proper muscle fiber connection and causes muscular dystrophy." (PMID 36684099, 2023). "A variety of mutations in the largest human gene, dystrophin, cause a spectrum from mild to severe dystrophin-associated muscular dystrophies." (PMID 35168641, 2022). "In recent years, an increasing number of antisense and gene therapies have been studied for the treatment of muscular dystrophy; however, few of these therapies focus on treating mutations arising in the N-terminal encoding region of the dystrophin gene." (PMID 35205302, 2022). "DMD, which is the most severe childhood form of dystrophy in the broader family of muscular dystrophies, is caused by mutations in the dystrophin gene encoding the dystrophin protein." (PMID 36077200, 2022). "Muscular dystrophy patients and dystrophin-deficient mice displayed an upregulation of RIPK3 which indicates necroptosis activation." (PMID 35990890, 2022). "DMD is a type of muscular dystrophy caused by a loss-of-function mutation in the Dystrophin (DMD) gene that encodes for a protein that has a crucial role in muscle structure." (PMID 35188098, 2022). "Dystrophin-associated muscular dystrophies include a spectrum of recessive X-linked muscle diseases that result from mutations in the dystrophin gene." (PMID 35168641, 2022). "Mutations in dystrophin and sarcoglycans result in different muscular dystrophies and can be associated with cardiomyopathy." (PMID 36505053, 2022). "Mutations or deletions of the DMD gene lead to muscular dystrophy, which currently lacks viable therapeutic treatment strategies." (PMID 34454586, 2021). "DMD is the most common and severe form of all muscular dystrophies, caused by mutations in the DMD gene, which prevents the synthesis of the dystrophin." (PMID 34831073, 2021). "The disease is caused by mutations in the dystrophin gene encoding the dystrophin protein and constitutes the most severe childhood form of the broader family of muscular dystrophies." (PMID 33619882, 2021). "Similar to the dachshunds of this report, a markedly elevated CK activity was also an incidental finding on pre-anesthetic blood screening prior to neuter from a family of Labrador retrievers with dystrophin-deficient muscular dystrophy." (PMID 33407862, 2021). "The system was implemented in healthy and diseased mouse tissues, including models of muscle myopathy seen with NF1-deficiency in mice and muscular dystrophy caused by dystrophin deficiency." (PMID 34935315, 2021). "Duchenne (DMD) and Becker (BMD) muscular dystrophy are X-linked recessive disorders produced by mutations in the DMD gene which encodes the protein dystrophin." (PMID 34177765, 2021). "The mdx mice are a widely used model of muscular dystrophy that feature a mutation in the murine dystrophin gene." (PMID 34935315, 2021).
muscular dystrophy (continued). "The most extensively studied muscular dystrophy in veterinary medicine involves dystrophin synthesis deficiency in the golden retriever, with several institutional colonies dedicated to basic research." (PMID 33502125, 2021). "DMD is the most common and severe form of lethal muscular dystrophy caused by mutations in the dystrophin gene." (PMID 34073503, 2021). "Since the woman is a carrier of DMD exons 16–29 deletion, the transmission of the deleted allele to a male child will result in muscular dystrophy, while the transmission of the duplicated allele can also be pathogenic." (PMID 33494189, 2021). "Dystrophinopathy is a spectrum of muscular dystrophies resulting from absolute to relative deficiency of dystrophin - a protein essential for muscle fiber integrity." (PMID 35070564, 2021). "Muscular dystrophies are caused by mutations in proteins that comprise the dystrophin protein complex (DPC) that anchors the cytoskeleton underlying the sarcolemma to the ECM and scaffolds signaling proteins." (PMID 33298880, 2020). "Historically, dystrophin represents the first costameric protein found to be associated with muscular dystrophy, displaying periodic association with costameres running transversal to the long axis of the myofiber." (PMID 33175853, 2020). "We searched for BMD cases with nonsense/frameshift mutations in DMD in the Japanese Registry of Muscular Dystrophy." (PMID 31919629, 2020). "The mdx mouse is one of the most common muscular dystrophy models, harboring a spontaneous mutation in the Dmd gene (encoding dystrophin) and presenting with a moderate muscle phenotype." (PMID 32130242, 2020). "A novel, de novo mutation in the DMD gene leading to a frameshift deletion of exons 8-34 was found in a Russian patient with muscular dystrophy." (PMID 31028078, 2019). "That the DMD is the most severe and common muscular dystrophy in China, and the dystrophin gene is the largest gene with a high rate of mutation, so Sanger sequencing of all the exons of dystrophin gene is very laborious and time‐consuming." (PMID 30938079, 2019). "The Dp427 transcript encodes the full-length dystrophin protein, whose altered expression or loss of function is responsible for muscular dystrophies like Duchenne and Becker myopathies." (PMID 31266185, 2019). "Mice with muscular dystrophy due to the mdx mutation in the dystrophin gene serve as model of human cardiomyopathy." (PMID 31468715, 2019). "The mdx mouse has a premature termination within exon 23 of DMD, leading to loss of dystrophin and muscular dystrophy." (PMID 29858053, 2018). "The finding represents a naturally-occurring mutation causing dystrophin-deficient muscular dystrophy in the dog." (PMID 29474464, 2018). "Histopathology and immunofluorescent stainings were consistent with muscular dystrophy resulting from dystrophin deficiency." (PMID 29474464, 2018). "Mutations in the gene encoding for the intracellular protein dystrophin cause severe forms of muscular dystrophy." (PMID 30360568, 2018). "Duchenne (DMD) and Becker (BMD) muscular dystrophies are caused by mutations in the DMD gene coding for dystrophin, a protein being part of a large sarcolemmal protein scaffold that includes the neuronal nitric oxide synthase (nNOS)." (PMID 29703249, 2018). "Histopathological, immunohistochemical and immunoblotting analyses of muscle biopsies were consistent with dystrophin-deficient muscular dystrophy." (PMID 29474464, 2018). "Aqp4, which is enriched in type II muscle fibers, has been shown to be associated with dystrophin and is lost or reduced in muscular dystrophy." (PMID 30089464, 2018). "Our study also lays the foundation for further probing of the mechanism of muscle function loss in dystrophin-deficient C. elegans, leading to knowledge translatable to human muscular dystrophy." (PMID 30396907, 2018).
muscular dystrophy (continued). "The efficient resealing of the dystrophin‐deficient sarcolemma by vesicular patching presents a key protective response in muscular dystrophy." (PMID 29679381, 2018). "Historically, germline DMD mutations have been associated with the development of Muscular Dystrophies." (PMID 27391342, 2017). "We should identify which type of cell responds to Jagged1 and which one of the Notch species is relevant for the rescue of muscular dystrophy in dystrophin-deficient dogs." (PMID 29194448, 2017). "DMD mutations in muscular dystrophy cluster in hotspot regions, which are mainly located on exons 45-53 and exons 2-20." (PMID 28947997, 2017). "In mice, Sarcospan (SSPN) plays important roles in muscular dystrophy and muscle force development by linked to sarcoglycans or as a component of the dystrophin-glycoprotein complex." (PMID 29141033, 2017). "Similar deleterious splice defects were previously reported for genes including DMD, C9orf72 and GR associated with muscular dystrophy, amyotrophic lateral sclerosis/frontotemporal dementia and small cell lung cancer respectively." (PMID 28187452, 2017). "We compared these with biopsies from a same-aged healthy subject (control) and from patients with muscular dystrophy caused by mutations in the dysferlin gene (dysferlinopathy) or in the dystrophin gene (dystrophinopathy)." (PMID 28676641, 2017). "In summary, the pathological analysis suggested that the DMD-modified pig displayed characteristic phenotypes of muscular dystrophy due to the deficiency of dystrophin." (PMID 27735844, 2016). "Muscle degenerative diseases such as muscular dystrophy (MD) are most commonly caused by mutations in genes that are part of the dystrophin-glycoprotein (DGC) complex or the integrin complex of proteins." (PMID 27669143, 2016). "Abnormal age- and muscle-dependent mTOR activation has been observed previously in the skeletal muscle of the mdx mouse, a mild model of dystrophin-deficient muscular dystrophy." (PMID 27257474, 2016). "Mutations in genes encoding proteins that are essential for muscle cell stability, such as components of the dystrophin-glycoprotein complex, weaken the sarcolemmal membrane and cause various types of muscular dystrophy." (PMID 27073590, 2016). "Specifically, 60 day old and adult dogs had an increase in type 1 fibers, suggesting that the type 1 preference is an aspect of dystrophic remodeling in dystrophin-deficient muscular dystrophy." (PMID 27430020, 2016). "An increase in the number of central nuclei is one of prominent features in the development of muscular dystrophy, which is caused by the loss of dystrophin." (PMID 28979820, 2016). "Fiber type changes in disease, with specific focus on muscular dystrophies caused by defects in the dystrophin glycoprotein complex, are discussed." (PMID 27430020, 2016). "For example, mutations that affect a protein called dystrophin-glycoprotein or integrin protein complexes can cause muscular dystrophy since these proteins normally keep the membrane anchored and stable when the muscle contracts and relaxes." (PMID 27669143, 2016). "The injection of Cas9, sgRNA, and homology-directed repair template into mouse zygotes has been shown to correct the dystrophin gene mutation responsible for muscular dystrophy in the germ line and prevent the development of muscular dystrophy in mutant mice." (PMID 25984354, 2015). "Muscular dystrophies are often caused by genetic alterations in the dystrophin-dystroglycan complex or its extracellular ligands." (PMID 26536238, 2015). "In fact, canine models of dystrophin deficient muscular dystrophy and X-linked myotubular myopathy are of tremendous value in the translation of new and promising therapies for the treatment of these diseases." (PMID 25664165, 2015).